SIRT1 (sirtuin 1)
Diseases named in the same sentence as SIRT1 in open-access papers (continued):
Sharing a sentence is not in itself a finding about the gene and the disease.
Hepatic steatosis (continued). "Moreover, mice models of hepatic steatosis display low levels of SIRT1." (PMID 26890260, 2016). "In addition to the regulatory effects of Sirt1 and Sirt6 on diabetes and hepatic steatosis, other sirtuins including Sirt2 and Sirt3 also demonstrate the possibility of acting as metabolic regulators, which suggests that sirtuins’ actions on metabolism seem to be, in part, overlapping and redundant." (PMID 25133775, 2014). "Therefore, statins, particularly simvastatin, might play a crucial role in ameliorating the progression of NAFLD, such as hepatic steatosis, inflammation and fibrosis, via regulating microRNA-34a/Sirtuin-1 pathway." (PMID 24098525, 2013). "Therefore, the protective action of carvacrol against hepatic steatosis might involve not only enhanced SIRT1-AMPK signaling, but also a decreased concentration of cholesterol ester." (PMID 23533470, 2013). "Therefore, we investigated whether the beneficial effects of exendin-4 treatment on fatty liver are mediated via Sirt1 in high-fat (HF) diet-induced obese C57BL/6J mice and related cell culture models." (PMID 22363635, 2012). "Second, apple polyphenols have been found to mitigate hepatic steatosis by promoting AKK abundance, an effect that depends on the activation of the SIRT1 pathway." (PMID 40176900, 2025). "Besides, studies have reported that inhibition of miR-34a may increase the levels of its downstream targets, including peroxisome proliferator-activated receptor-α (PPARα) and Sirtuin protein family-Sirtuin1 (SIRT1) that were related to fatty acid oxidation thereby alleviating liver steatosis." (PMID 41223206, 2025). "SIRT1-mediated signaling pathways have been shown to attenuate key pathological features of MASH, including hepatic steatosis, inflammation, fibrosis, and cellular senescence." (PMID 40052151, 2025). "In addition, SIRT1 contributes positively to the regulation of hepatic lipid metabolism, the management of oxidative stress in the liver, and the prevention of liver inflammation by deacetylating various transcriptional regulators, thereby mitigating the progression of fatty liver diseases." (PMID 40427561, 2025). "Of note, SIRT1 activation in mice treated with the ER stressor tunicamycin prevented the increase in hepatic VLDLR levels and significantly attenuated hepatic steatosis." (PMID 38807218, 2024). "BBR alleviates hepatic steatosis and controls energy balance in mice by inducing autophagy and fibroblast growth factor (FGF)-21, where SIRT1 is critical to this process." (PMID 38957396, 2024). "Salvianolic acid B is capable of modulating the SIRT1-dependent deacetylation of HMGB1, thereby offering protection against hepatic steatosis and inflammation induced by either a high-fat diet or palmitic acid." (PMID 39605910, 2024). "In our study, supplementation with the precursor of NAD+, NR, prevented hepatic steatosis induced by Nic plus HFCS (Coke), involving specific molecular signaling downstream of NAD+, Sirt1, and PGC1α, to reverse mitochondrial damage." (PMID 38756999, 2024). "Given the excellent performance of PCE in reversing HFD-induced hepatic steatosis, we further determined the expression level of AMPK/SIRT1 in the liver tissue of each group by Western blot and qPCR." (PMID 39949396, 2024). "Here, we identified the high binding affinity of 8PG with AMP-activated protein kinase (AMPK) and sirtuin 1 (SIRT1), which acts as a potent AMPK activator that counteracts hepatic steatosis." (PMID 39273677, 2024). "Higher NAD+ levels can enhance the activity of sirtuin 1 (SIRT1) and sirtuin 3 (SIRT3), which have been reported to protect mice from fatty liver diseases such as NAFLD." (PMID 38786029, 2024). "In HFD model, liver-specific Sirt1 knockout impaired PPARα/PGC-1α signaling and reduced fatty acid oxidation, thereby resulting in increased hepatic steatosis." (PMID 37834101, 2023).
Hepatic steatosis (continued). "Continued on the previous study, we identified that ATF6 ameliorates liver steatosis and inflammation by upregulating CBS expression and H2S synthesis via SIRT1 sulfhydration." (PMID 38007457, 2023). "SIRT1 deacetylates and inhibits SREBP1c activity, and transgenic mice overexpressing SIRT1 are protected from HFD-induced hepatic steatosis." (PMID 38201252, 2023). "In contrast to SIRT1 and SIRT6, SIRT7 functions as a positive regulator of hepatic lipid accumulation, and Sirt7 KO mice are resistant to HFD-induced fatty liver." (PMID 38201252, 2023). "The administration of lycopene, another carotenoid, protected against hepatic steatosis and inflammation in BCO2-expressing mice through the activation of SIRT1 and PPARγ signals." (PMID 37018237, 2023). "Our findings demonstrate that H8 alleviates hepatic steatosis, by inhibiting 11β-HSD1, which activates the AMPK/SIRT1 signaling pathway." (PMID 35684158, 2022). "Mice that received erythropoietin showed increased level of SIRT1 and LC3 with alleviating hepatic steatosis." (PMID 35909524, 2022). "The intracellular NAMPT inhibitor FK866 promoted liver steatosis in HFD-fed mice and hepatic lipid accumulation in vitro via the sirtuin 1 (SIRT1)/sterol regulatory element-binding protein 1 (SREBP1)/fatty acid synthase (FASN) pathway." (PMID 36009862, 2022). "Accordingly, transgenic mice overexpressing SIRT1 are protected against various metabolic disorders, including glucose intolerance, high-fat diet (HFD)-induced fatty liver, type 2 diabetes, age-induced cancer, osteoporosis, and cardiac hypertrophy." (PMID 35956321, 2022). "Alcohol consumption induces fatty liver by downregulating AMPK and SIRT1, increasing the acetylated form of SREBP-1c, and inhibiting fatty acid oxidation." (PMID 36557739, 2022). "Activation of SIRT1 and AMPK improves hepatic steatosis by enhancing carnitine palmitoyltransferase 1 (CPT-1) expression and promoting fatty acid β-oxidation for lipolysis." (PMID 36557739, 2022). "Some fruits and their bioactive compounds ameliorate fatty liver disease by promoting the inhibition of apoptosis, inflammation, and oxidative stress and alleviate hepatic steatosis by regulating AMPK and SIRT1 signaling." (PMID 36552704, 2022). "Our study demonstrates that PREP disruption dynamically ameliorates hepatic steatosis and inflammation by regulating intestinal dysbiosis, activating the AMPK/SIRT1 pathway, and inhibiting the inflammatory signaling pathway." (PMID 34095107, 2021). "Sirtuin 1 (SIRT1), an NAD+-dependent deacetylase, plays a vital role in hepatic steatosis and inflammation." (PMID 34483906, 2021). "Similarly, the repression of SIRT1 in mouse liver is sufficient to induce hepatic steatosis, an effect that might be mediated by the key regulators of glycolysis and lipolysis, peroxisome proliferator-activated receptor (Ppar)-γ and Pparα as Sirt1 deletion impairs their function." (PMID 34069012, 2021). "It is known that lipogenesis can be promoted by SIRT1-mediated inhibition of AMPK phosphorylation and activation, leading to hepatic steatosis." (PMID 34095107, 2021). "Decreased histone acetylation further impairs the Sirtuin 1 (SIRT1)–AMPK pathway, a hepatic lipid metabolism pathway, and results in fatty liver and advanced fibrosis formation." (PMID 34068269, 2021). "Resveratrol alleviated alcohol-induced fatty liver disease in male mice by increasing the activity of AMPK and SIRT1, which are involved in the control of liver lipid metabolism pathways." (PMID 33805795, 2021). "Hepatocyte-specific deletion of SIRT1 disrupts DEPTOR signaling pathway, promotes mTORC1 activation, and exacerbates the development of alcoholic fatty liver and liver injury in mice." (PMID 33162823, 2020). "In this study, we explored the effect of EX-527, a SIRT1-selective inhibitor, on the progression of high-fat diet (HFD)-induced fatty liver or fibrosis in Zucker diabetic fatty (ZDF) rats." (PMID 32365537, 2020).
Hepatic steatosis (continued). "Lower enzyme activities of SIRT1, PGC-1α, Cu/Zn SOD, CAT, GSH-Px, SREBP-1c and Mn SOD (p < 0.05) and concentration of reactive oxygen species (ROS) were observed in dairy cows with fatty liver." (PMID 32230804, 2020). "The SIRT1 pathway has also been shown to play an essential role in the exenatide-induced alleviation of the lipid-induced ERS and hepatic steatosis." (PMID 32070320, 2020). "Based on these results it can be concluded that SIRT1/PGC-1α/SREBP-1c and redox are involved in fatty liver dairy cows by promoting hepatic fatty acid synthesis, impairing fatty acid β-oxidation and reducing lipid transport." (PMID 32230804, 2020). "But in Sirt1+/− mice on HFD, body weight, fat content and hepatic steatosis are increased, adipose tissue macrophage infiltration and expression of inflammatory genes, indicated by the expression of F4/80, TNF-α, IL-1, and IL-6, are enhanced in epididymal fat." (PMID 33390968, 2020). "As expected, overexpression of hepatic NAMPT led to reduced TG concentrations and serum ALT, AST levels, but this effect was abolished when SIRT1 was knocked down, suggesting SIRT1 mediates the effects of NAMPT on ethanol-induced liver steatosis and injury." (PMID 30794635, 2019). "In the present study, we examined the effect of TSF on hepatic steatosis in NAFLD models and the role of AMPK/SIRT1-mediated autophagy during this process." (PMID 31105592, 2019). "In contrast, EX 527 intervention effectively inhibited the increased expression of SIRT1 induced by SLBZS, and partly diminished the beneficial effects of SLBZS on hepatic steatosis, liver blood flow and biochemical parameters in rats fed a high-fat diet." (PMID 31683679, 2019). "Other research has found that the hepatocyte-specific deletion of SIRT1 undermined the activity of PPAR-α, which decreased fatty acid oxidation and led to development of hepatic steatosis and inflammation." (PMID 30995792, 2019). "In comparison with placebo, GC significantly increased Sirt1 and decreased hs-CRP, TNF-α, IL-6, ALT, and the degree of fatty liver (P < 0.05)." (PMID 30263038, 2018). "Taken together our results demonstrated that MGF attenuated excessive liver fat deposition and protected against hepatic steatosis by suppressing SREBP-1c related lipogenesis, promoting lipolysis and fatty acid oxidation via regulating SIRT1/AMPK pathway." (PMID 29563875, 2018). "Specific knockout of SIRT‐1 in the liver (SIRT1 LKO) decreases fatty acid oxidation, which leads to body weight gain and the development of hepatic steatosis." (PMID 28699690, 2017). "Activation of ChREBP is associated with increased lipogenesis, leading to a marked increase in hepatic steatosis that is known to increase the expression of PPAR-γ, a lipogenic factor capable of suppressing SIRT1 expression." (PMID 28558013, 2017). "Based on these reports, we used an HFD-induced rat model of hepatic steatosis to implement caloric restriction as a lifestyle modification and resveratrol as a drug therapy for lipid metabolism and study whether both forms of treatment act through SIRT1-mediated autophagy induction." (PMID 28817690, 2017). "In this way, SIRT1 and SIRT3 are involved in the balance of metabolic and hepatic steatosis regulation through the epigenetic modification." (PMID 25751727, 2015). "We observed that metformin ameliorates hepatic steatosis in the HED liver, along with an increased expression of pACC and SIRT1, a finding which is consistent with previous studies." (PMID 25895126, 2015). "We, for the first time, demonstrated that BM extract attenuated hepatic steatosis in mice by enhancing hepatic FGF21 and AMPK/Sirt1 signaling." (PMID 24189525, 2013). "Mounting evidence suggests that a high-fat diet (HFD) causes enhanced lipogenesis and impaired fatty acid oxidation by inhibiting AMP-activated protein kinase (AMPK) activation through Sirtuin 1 (SIRT1), leading to the development of hepatic steatosis." (PMID 23533470, 2013).
Hepatic steatosis (continued). "Activation of PPARα by WY14643 ameliorated hepatic steatosis through increasing lipids oxidation promoting genes CYP4A10, CYP4A14, FGF21, adiponectin, SIRT1 and PGC-1α expression, and suppressing fatty acid synthesis promoting genes FAS and PI3K expression." (PMID 22208561, 2011). "Treatment of HepG2 cells and mice with Sirt1 activators (e.g., resveratrol and SRT1720) showed therapeutic potential for the treatment of fatty liver." (PMID 21373642, 2011). "Regarding the involvement of Sirt1 in the RGZ's action, a recent paper using a mouse model of alcoholic fatty liver showed that RGZ improves alcoholic fatty liver and stimulates adiponectin-Sirt1-AMPK signaling." (PMID 21373642, 2011). "Interestingly, modest overexpression of SIRT1 also protects mice against high-fat diet induced glucose intolerance and hepatic steatosis, so that SIRT1 may represent a promising future pharmacological target to prevent the metabolic sequelae of chronic exposure to a high-fat diet." (PMID 19014491, 2008). "These in silico data suggest that the pharmacological action of 8PG may involve the regulation of lipid metabolism, such as hepatic steatosis, by targeting AMPK, which is activated by phosphorylation, and SIRT1." (PMID 39273677, 2024). "Furthermore, curcumin activates the AMPK/SIRT1 signaling pathway and regulates ACC-CPT-1 and SREBP1-FASN to alleviate hepatic steatosis by suppressing 11 beta-hydroxysteroid dehydrogenase (11β-HSD1)." (PMID 38313314, 2024). "In addition, resveratrol, a SIRT1 enhancer, stimulated the expression of SIRT1 and phosphorylation of AMPK, resulting in the inhibition of lipid accumulation in the liver and recovery from hepatic steatosis in obese mice." (PMID 39273677, 2024). "Methyl FA could inhibit lipid synthesis through AMPK and FoxO1 signal pathways while promoting lipid oxidation via the SIRT1/PPAR-α/CPT-1α axis, ultimately attenuating ethanol-induced hepatic steatosis." (PMID 39594419, 2024). "The decreased hepatic SIRT-1 expression after MS induction is consistent with the previous researchers who reported that the pathophysiology in CVS, T2DM, liver steatosis, and MS in mice with high fatty acid enriched diet is due to reduced SIRT-1 expression and activity." (PMID 36991247, 2023). "SIRT1 may ameliorate NAFLD and plays important roles in reducing hepatic steatosis and regulating mitochondrial function involved in the process of NAFLD." (PMID 37367070, 2023). "In addition, pharmacological stimulation of SIRT1 attenuates hepatic steatosis through PRKA-independent, SIRT1-mediated autophagy and attenuates hepatic ischemia-reperfusion injury by restoring mitochondrial function and enhanced autophagy." (PMID 36008973, 2022). "In addition, we proved that AMPK is a downstream protein of SIRT1, which mediates the GS-induced protection against ANIT-accelerated hepatic steatosis." (PMID 36235592, 2022). "Moreover, MG5311 suppressed hepatic steatosis by regulating SREBP-1c and PPARα expression via upregulating the SIRT1 pathways." (PMID 36557739, 2022). "NAFLD experimental animal model studies show that SIRT1, as a negative regulator of UPR signals, inhibits mechanistic target of rapamycin complex 1 (mTORC1) and endoplasmic reticulum stress, reduces hepatic steatosis, improves insulin resistance, and restores glucose homeostasis." (PMID 36008973, 2022). "In addition, RSV, when administrated alone, has been reported to alleviate alcohol-induced fatty liver disease in male mice by increasing the activity of the AMPK and SIRT1 pathways." (PMID 36432440, 2022). "Unexpectedly, the effects of metformin on reducing body weight and alleviating hepatic steatosis were not impaired in Sirt1 heterozygous knockout (Sirt1+/−) mice." (PMID 34483906, 2021). "No significant changes were observed in the grade of liver steatosis, glycemic parameters in serum, high-density lipoprotein cholesterol, and sirtuin-1 levels (p > 0.05)." (PMID 32823621, 2020).
Hepatic steatosis (continued). "SIRT1 is also involved in controlling hepatic lipid metabolism, moderating oxidative stress in liver and protection from HFD induced hepatic inflammation, glucose intolerance and hepatic steatosis." (PMID 32335547, 2020). "One study also suggested that the favorable effects of a bitter melon water extract on increasing insulin sensitivity and attenuating hepatic steatosis may be mediated by enhanced AMP-activated protein kinase (AMPK) and sirtuin (SIRT1) signaling." (PMID 32354072, 2020). "Phloretin could also regulate lipid metabolism by increasing the Sirt1/AMPK pathway, improving liver steatosis in obese mice." (PMID 33014333, 2020). "Therefore, stimulating the activation of the Sirt1/AMPK pathway will reduce lipid accumulation in the liver and improve hepatic steatosis in obese and overweight individuals." (PMID 33014333, 2020). "Low expression of sirtuin 1 (SIRT1), a NAD-dependent histone deacetylase, was indicated to promote hepatic fatty acid synthesis and inhibit fatty acid β-oxidation in dairy cows with mild fatty liver disease." (PMID 32586350, 2020). "Therefore, chronic alcohol exposure impairs SIRT1/SREBP-1 axis in a miR-217 dependent manner and ultimately induces hepatic steatosis." (PMID 30634538, 2019). "The results revealed that the SIRT1/AMPK pathway is involved in the functions of the three flavonones, and the most effective flavonone against hepatic steatosis might be PCBG, followed by MPG and PCB." (PMID 30154382, 2018). "The results of protein expression including upregulation of SIRT1 and PGC1 and downregulation of FAS and FABP4 in liver tissue of the NDS group provided evidences to support amelioration of hepatic steatosis of APS1 might through the gut-liver axis." (PMID 29670255, 2018). "GC supplementation could improve some biomarkers related to fatty liver including inflammation, ALT, and Sirt1 in overweight/obese NAFLD patients." (PMID 30263038, 2018). "Previously, it was reported that a decrease in SIRT1 expression inhibits SREBP1 and lipogenesis, decreases PPARα levels which leads to the reduced use of fat as an energy source, and induces fat accumulation and hepatic steatosis." (PMID 30363947, 2018). "This hypothesis is supported by the fact that the lowest SIRT1 mRNA levels can be found in adipose tissues from obese patients diagnosed with T2DM and severe hepatic steatosis." (PMID 27104517, 2016). "Although these studies are restricted to non-alcoholic hepatic steatosis, we hypothesize that PPARγ and its downstream effector MGAT1 may play a role in alcohol-induced hepatic lipid accumulation if SIRT1 affects hepatic PPARγ during ethanol metabolism." (PMID 27404390, 2016). "In a parallel study, we showed that lack of FGF21 exacerbated chronic alcohol exposure-induced fatty liver through SIRT-1-mediated fatty acid β-oxidation (unpublished observations)." (PMID 26092866, 2015). "We are the first to demonstrate that the SIRT1/HMGB1 pathway is a key therapeutic target for controlling NAFLD inflammation and that SalB confers protection against HFD- and PA-induced hepatic steatosis and inflammation through SIRT1-mediated HMGB1 deacetylation." (PMID 26525891, 2015). "The effects of exendin-4 on Sirt1 expression as a mechanism of reducing fatty liver have not been previously reported." (PMID 22363635, 2012). "Considering the previous observations as well as our findings, it can be speculated that both Sirt1 and Sirt6 are involved in the RGZ-mediated amelioration of hepatic steatosis." (PMID 21373642, 2011). "Like other Sirt1 activators, RGZ administration increased Sirt6 expression and phosphorylation levels of LKB1 and AMPK, and provided protection from hepatic steatosis, suggesting that RGZ may act as a Sirt6 activator and a therapeutic strategy for NAFLD." (PMID 21373642, 2011).